PTGS2 (prostaglandin-endoperoxide synthase 2)
Diseases named in the same sentence as PTGS2 in open-access papers (continued):
Sharing a sentence is not in itself a finding about the gene and the disease.
tumor (continued). "Prostaglandin intra peroxidase synthetase 2 (PTGS2) is one of the key enzymes mediating new prostaglandin synthesis and has been shown to play an important role in tumor development." (PMID 37032823, 2023). "The pleiotropic nature of PTGS2 encompasses a wide range of effects, including the stimulation of angiogenesis and tumor cell proliferation." (PMID 37762335, 2023). "Accordingly, CHAC1 and PTGS2 mRNA expressions and lipid peroxidation marker 4HNE in tumor tissues were all elevated by the combination therapy compared with PD-1 blockade alone, and these inductions were also reversed by liproxstatin-1 co-treatment." (PMID 37553341, 2023). "A unique observation of our study is the substantial overlap of genes involved in tumor manifestation/association with the genes involved in cardiotoxicity and neurotoxicity such as ESR1, PTGS2, LTA and KDR." (PMID 37069190, 2023). "Ptgs2 expression was significantly higher in the wasting eWAT of tumor-bearing mice than in the eWAT of control animals." (PMID 36973755, 2023). "Previous research has expressed that PTGS2 involved the regulation of angiogenesis in plentiful cancer and tumor diseases." (PMID 36768450, 2023). "PGE2 can inhibit anti-tumor immunity in tumor microenvironment, PTGS2, as the key enzyme in PGE2 biosynthesis, was also highly expressed in macrophages co-cultured with hybrid cells." (PMID 37138326, 2023). "Our previous data demonstrated that CTCF and PACERR bind to the promoter region of PTGS2, and both of them are indispensable for the M2 polarization and pro‐tumour functions of TAMs." (PMID 35184402, 2022). "PTGER4 is a major PGE2 receptor and is involved in the feed-forward pathway that upregulates STAT3 phosphorylation and activates PTGS2 expression in the tumor cells of CRC." (PMID 36142151, 2022). "PTGS2 was upregulated in tumor tissues and promoted tumor progression and chemotherapy resistance in various cancers." (PMID 36733386, 2022). "EGFR entering the nucleus can promote the expression of c-myc, cyclin D1, and PTGS2, and can contribute to tumor cell proliferation." (PMID 35603146, 2022). "PTGS2 plays a key role in antitumor immune suppression, and its immune suppressive functions lead to tumor immune evasion and poor survival." (PMID 36561345, 2022). "Recently, it was found that PTGS2 regulates HIF2α under hypoxic conditions to promote tumor development and resistance to sorafenib in HCC." (PMID 35740546, 2022). "PTGS2 can induce an immunosuppressive state in the tumor environment by inducing the recruitment of immune cells into tumor tissues, thereby guiding the immunophenotype and favoring the activation of cancer cells." (PMID 36203533, 2022). "In summary, we assigned the effects of SQSTM in tumor cells as a risk factor and the effects of other 5 genes (GDF9, LINC01125, PTGS2, GVINP1, and TMEM64) in immune cells as protective factors." (PMID 35436939, 2022). "PTGS2 activates the NF-κB signaling pathway, leading to tumor cell proliferation and tolerance to radiotherapy." (PMID 36231068, 2022). "Quantitative polymerase chain reactionanalysis of the mRNA expression in U-87 MG and SKOV-3 tumor tissuesfrom 15-treated mice showed the presence of Ptgs2/Nfe2l2/Sat1/Akr1c1/Gpx4 genes correlated with ferroptosis in bothgroups." (PMID 36395526, 2022). "PTGS2 has been shown to promote tumor development in CCA, while its inhibition potentiated conventional chemotherapy effects." (PMID 36733386, 2022). "COX-2 (PTGS2) inhibition has been addressed during mammary involution, demonstrating reduced lung metastasis due to disruption of lymphatic dissemination of tumour cells." (PMID 35420674, 2022). "The suppression effect of MAEL knockout in tumor aggressiveness was rescued in PTGS2 overexpression HCC cells." (PMID 35740546, 2022). "PTGS2 can also mediate cell proliferation, angiogenesis, apoptosis, invasion, and immunosuppression to increase tumor progression." (PMID 35754680, 2022).
tumor (continued). "We also identified a rare subset of cells resembling mesenchymal stem cells (MSCs) that expressed Ptgs2 and that were previously shown to establish a tumor-promoting niche through provision of PGE2 and induction of Yap." (PMID 35085231, 2022). "Recently, Markosyan and co-workers identified the ephrin-A receptor 2/TGF-β/SMAD/PTGS2 axis as a key tumor-intrinsic driver of immunosuppressive TME in spontaneous PDAC mouse model." (PMID 35945203, 2022). "Intriguingly, brain metastatic cells were found to have a tumor metabolic phenotype, similar to that of CSF tumor cells owing to increased PTGS2 expression, which assisted cancer cells in passing through tight capillary connections during tumor colonization." (PMID 35513201, 2022). "In general, the effects of SQSTM in tumor cells are assigned as a risk factor, while the effects of the other 5 genes (GDF9, LINC01125, PTGS2, GVINP1, and TMEM64) in immune cells are assigned as protective factors." (PMID 35436939, 2022). "Cyclooxygenases (Ptgs1, Ptgs2) are expressed primarily in epithelial to mesenchymal transition-like tumor cells, myeloid cells, neutrophils, and fibroblasts." (PMID 36277993, 2022). "The results show PMEPA1 were mainly expressed in basal tumor cells, CAFs, endothelial cells, muscle cells, and urothelial cells, TGFB1 were mainly expressed in basal tumor cells, CAFs, and TAMs, PTGS2 were hardly expressed in those cells." (PMID 34777336, 2021). "PTGS2 is expressed in many tumors and plays a role in tumorigenesis, tumor metastasis, and tumor treatment resistance." (PMID 34124047, 2021). "The present study confirmed the profound increase in pro-inflammatory markers (Il6, Il1β, and Ptgs2) in tumor compared to peri-tumoral tissue in mice of all genotypes." (PMID 34526660, 2021). "The tumor-infiltrating regulatory T cells (Treg) counts were positively correlated with intra-tumoral PTGS2 expression, particularly in patients with lymph node-negative NSCLC." (PMID 35096012, 2021). "In fact, recently, PTGS2 overexpression in tumor tissues of CRC patients (immunohistochemical and qPCR method) was closely associated with clinico-pathological data demonstrating a more pronounced expression in males vs. females." (PMID 34067294, 2021). "It has biological activities such as inhibiting cell apoptosis, promoting cell proliferation, and promoting angiogenesis, indicating that PTGS2 plays an essential role in tumor occurrence and development." (PMID 34211578, 2021). "In order to explore the role of PTGS2 in tumor cells, we used celecoxib, a selective inhibitor of PTGS2, to detect cell viability in OCM1 cells." (PMID 34124047, 2021). "Studies have shown that the anti-tumor effect of 5-FU has a certain correlation with PTGS2, NR3C2, CA2 and MMP1." (PMID 34125845, 2021). "Immunohistochemical analysis of 4HNE and PTGS2, markers of lipid peroxidation and ferroptosis, supported the synergistic effect of sorafenib in inducing tumor ferroptosis in HCC cells with enhanced activation of YAP in vivo." (PMID 34977009, 2021). "The heatmap showed that more than half of the genes were downregulated in tumor tissue, and consistent with the univariate Cox regression analysis, they represented a better prognosis, including PTGS2, ACO1, DPP4, CRYAB, PRKCA, ACSL4 and AKR1C3." (PMID 34475496, 2021). "T cell depletion abolished the tumor growth suppression afforded by Ptgs2 KD or celecoxib, which indicates that the tumor suppression of PTGS2 is T cell dependent." (PMID 33718229, 2021). "Our observations suggested a possible subgrouping of CRC on the basis of stromal, or tumor-derived PTGS2, the former modulated by IL1β, with a prognostic significance, the latter relatively independent." (PMID 32168749, 2020). "It has been shown that in GBM, PTGS2/COX-2-positive cells accumulated in perinecrotic regions of the tumor." (PMID 32823815, 2020).
tumor (continued). "PTGS2 is an immediate-early response gene induced in response to mitogens, tumor promoters, cytokines, growth factors, and inflammatory stimuli." (PMID 32190085, 2020). "Due to the possible positive influence on patient OS of an intermediate PTGS2 expression in the luminal tumor stroma, we propose further validation of this marker on larger cohorts." (PMID 32168749, 2020). "We attempted to overcome this limitation quantifying gPTGS2 levels in CRC lysates, comparing them with IHC-scored, tumor, or stroma-derived PTGS2." (PMID 32168749, 2020). "The main IPA analyses predicted outcomes due to combined downregulation of c-MET and PTGS2 by OC treatment in NSCLC include the suppression of tumor cell proliferation, migration and metastasis and induction of tumor cell death." (PMID 32545325, 2020). "While this datum has no significant prognostic implications, it suggests distinct roles for stromal and tumor PTGS2." (PMID 32168749, 2020). "Equally, parental Ptgs2+/+ MC38 colorectal cells showed evidence of delayed tumor growth in GPP mice." (PMID 33220234, 2020). "On the contrary, an immediate divergence of curves was observed when CRC with putative stroma-derived PTGS2 were compared to CRC with putative tumor-derived PTGS2." (PMID 32168749, 2020). "PTGS2 levels were also evaluated by the same antibody in immunohistochemistry (IHC), distinguishing tumor-derived from stroma-derived PTGS2." (PMID 32168749, 2020). "Another molecule predicted is PTGS2, which encodes the COX-2 enzyme and is expressed in many tumor types." (PMID 32832554, 2020). "PTGS2-positive cells of the stromal component almost invariably localized in the luminal area of the tumor, with a strong intensity of staining." (PMID 32168749, 2020). "Second, ablation of Ptgs2 in B16F10 cells was associated with reduced myeloid-derived suppressor cell differentiation in vitro, and inhibited tumor development and metastasis in vivo." (PMID 33121001, 2020). "We quantified the 72 kDa, CRC-associated, glycosylated form of PTGS2 in 100 frozen CRC specimens and evaluated PTGS2 localization by IHC in the same tumors, scoring tumor epithelial-derived and stroma-derived fractions." (PMID 32168749, 2020). "Despite the different numbers of treated and untreated samples analyzed and the diverse levels of gene expression detected in the tumor samples, significantly higher PTGS2 and PTGES was evident in tumors from treated patients." (PMID 32967672, 2020). "Glycosylated PTGS2 can be quantified with high sensibility in tissue lysates, but the expression in both tumor and stromal cells limits its use for predictive purposes." (PMID 32168749, 2020). "PTGS2 is able to induce immune cell recruitment into the tumor tissue to promote an immunosuppressive state in the TME in favor of cancer cell activation." (PMID 31920649, 2019). "Adipocytes produce pro-inflammatory cytokines, such as TNF-α and IL6, that induce pro-tumorigenic cyclooxygenase 2 (COX2 or PTGS2) expression, causing the production of prostaglandin E2 (PGE2) that promotes tumor progression." (PMID 31443386, 2019). "In fact, PTGS2/PGE2 released from cancer cells to this milieu suppresses host immunological responses to tumor‐derived antigens by inducing accumulation of immunosuppressive cells like MDSCs." (PMID 31920649, 2019). "We compared the CXCR4 and PTGS2 expression in the tumors with the expression in the starting cell lines and observed a dramatic increase in tumor tissue for all samples except the MDMX knockdown cells." (PMID 30642351, 2019). "It seems that the secreted PGE2 catalyzed by PTGS2 contributes to tumor growth via stimulation of the surrounding cells in tumor microenvironment." (PMID 31440159, 2019). "The co-expression of PTGS2 gene and M2 markers in human thyroid carcinoma highlights the possibility to counteract tumor growth through COX-2 inhibition." (PMID 31113465, 2019).
tumor (continued). "More interestingly, it has been recently shown by our group that inhibition of PTGS2 enhances the anti-tumor activity of PD-1/PD-L1 based immunotherapy." (PMID 31920649, 2019). "It remains to be determined if PTGS2 upregulation plays a role in the tumor-suppressive effects of DKK3." (PMID 29843383, 2018). "miR-21 and COX-2 (PTGS2) mRNA levels were higher in the tumor samples than normal tissue, whereas 15-PGDH (HPGD) mRNA was significantly lower in the tumor samples of the TCGA cohort." (PMID 30531928, 2018). "Reduced PTGS2 decreases the suppression of tumor cell apoptosis and the promotion of tumor cell invasion." (PMID 29954406, 2018). "MiR-101 confers a role as a tumor suppressor via direct inhibition of prostaglandin-endoperoxide synthase 2 (COX-2) mRNA translation at the post-transcriptional level in CRC, or directly targeting ZEB1 to inhibit the proliferation and migration of CRC cells." (PMID 30227605, 2018). "PTGS2 is overexpressed in many cancers and was shown to play role in enhancing tumor progression and angiogenesis [reviewed in Ref." (PMID 29963047, 2018). "Two additional genes (CD14 and CSNK2A1) were dysregulated in MSS tumours and two genes (CARD11 and VCAM1) were downregulated and six genes were upregulated (LYN, TICAM2, ICAM1, IL1B, CCL4 and PTGS2) in MSI tumours." (PMID 29188362, 2018). "The expression of PTGS2 (COX2) can influence the physical properties of the tumor microenvironment including human breast cancer cells through mechanotransduction." (PMID 28415743, 2017). "So far, PTGS2, a gene encoding cyclooxygenase-2 (COX-2), is the unique widely used marker for erastin or RSL-3-induced ferroptosis in tumor." (PMID 29375387, 2017). "Further investigations are warranted to analyze interactions of multiple cell types that exist in the tumor microenvironment, and to examine the dual blockade of the PTGS2 and immunosuppressive pathways." (PMID 29152088, 2017). "Inhibition of PTGS2 or EGFR signaling is known to sensitize tumor cells to TNFSF10-mediated apoptosis." (PMID 28686677, 2017). "IL-11, a downstream target of PTGS2 and a potent driver of tumor progression in CAC, was significantly reduced in inflamed MDR1A KO tumors compared to WT tumors." (PMID 28686677, 2017). "We verified the efficacy of anti-IL-1R1 in vivo by measuring the relative expression of IL-1-responsive genes and saw a significant reduction in the expression of Il6, Il1b and Ptgs2 in tumours from anti-IL-1R1-treated mice relative to IgG-treated mice." (PMID 27708283, 2016). "Genes that enable tumor cells to extravasate and survive at the secondary tissue site contribute to metastasis progression including prostaglandin G/H synthase 2 (PTGS2), epiregulin, and angiopoietin-like 4 (ANGPTL4)." (PMID 27600078, 2016). "PPARγ agonists reduce mammary carcinogenesis, which correlates with induction of PTEN and BRCA1 tumor suppressor activity, as well as reduction of inflammation via the Cox2/Ptgs2 pathway." (PMID 28077942, 2016). "The PTGS metabolic pathway is aberrantly regulated in cancer, being the overexpression of PTGS2 a major feature of many tumor types." (PMID 26207152, 2015). "In one study, including only 36 patients, high methylation of PTGS2 was found to indicate a more than four-fold increased risk of BCR after adjusting for Gleason score, tumor stage, and pre-operative PSA in multivariate analysis." (PMID 25238417, 2014). "PTGS2 is involved in carcinogenesis, immune response suppression, inhibition of apoptosis, angiogenesis and tumor cell invasion and metastasis." (PMID 23374284, 2013). "PTGS2 is rapidly induced by growth factors, inflammatory cytokines, and tumor promoters, and it primarily catalyzes PG synthesis in cells involved in both local and systemic inflammatory responses." (PMID 23967159, 2013). "PTGS2 expression, which is undetectable in most normal tissues, is induced in response to hypoxia, inflammatory cytokines, tumor promoters, growth factors and other stressors." (PMID 23374284, 2013).
tumor (continued). "In contrast, overexpression of PTGS2 (COX-2) in mouse intestinal epithelium promotes tumor growth in AOM-treated mice." (PMID 24213116, 2011). "Genetic studies demonstrate that deletion of PTGS2 (COX-2) gene results in decreased tumor formation in both small intestine and colon of ApcMin mice as well as in ApcΔ716 mice." (PMID 24213116, 2011). "The levels of PGE2 in tumor tissues depend on the relative rates of PTGS2 (COX-2)/PGE synthase-dependent biosynthesis and hydroxyprostaglandin dehydrogenase 15-(NAD) (HPGD, also called as 15-PGDH)-dependent degradation." (PMID 24213116, 2011). "Coincident with enhanced PTGER4-mediated tumour growth we found elevated expression of PTGS2 in PTGER4 xenografts compared with WT xenografts." (PMID 21589857, 2011). "IL8 and IL6, both of which were enriched in our hemangiosarcoma samples, are recurrently associated with inflammation that "benefits" tumors, and PTGS2 (a.k.a., COX-2) is the single most common tumor-associated pro-inflammatory mediator." (PMID 21062482, 2010). "Genes that were over-expressed in tumor versus normal brain in animals fed a SD (Serpinb1b, Cygb, Mpp4 and Ptgs2) were under-expressed in tumor from animals fed a KD." (PMID 20831808, 2010). "Increased expression of PTGS2 occurs in multiple cells within the tumor microenvironment, which can affect angiogenesis." (PMID 18726958, 2008). "To determine whether LOC610012 exerted its tumor-suppressive effect through PTGS2, we performed a PTGS2 rescue experiment." (PMID 40643495, 2025). "These correlations were moderate to strong as observed in the TCGA-COAD RNA-seq cohort (CD274 vs. PTGS2, R = 0.48; CD8A vs. CD274, R = 0.67) and similar when validated in the E-MTAB-12,862 cohort, comprising over 1,000 CRC tumor samples (CD274 vs. PTGS2, R = 0.47; CD8A vs. CD274, R = 0.61)." (PMID 40958118, 2025). "Ultimately, we identified Acacetin and Asperglaucide as the most effective pharmacologically active ingredients in YYFZBJS for the treatment of NPC, suggesting that they may exert anti-tumor effects through the modulation of PTGS2 and CCND1 expression." (PMID 40302810, 2025). "In the DEN‐initiated HCC model, PTGS2 expression was significantly suppressed in tumours, indicating that ferroptosis is suppressed in HCC, and activation of ferroptosis might be a potential strategy to inhibit HCC progression." (PMID 40088428, 2025). "PTGS2 is a highly inducible isoenzyme that can be rapidly upregulated by various pro-inflammatory factors, including cytokines, tumor promoters, and mitogens, particularly in cells involved in inflammation, pain, fever, tumors, Alzheimer’s disease, or osteoarthritis." (PMID 40643495, 2025). "Moreover, similar to NTT tumours, YUMM1.7OVA RTT tumours with Ptgs2 KO or IRF3/7 overexpression were controlled in Rag2–/–Batf3–/– mice, which lack cDC1s." (PMID 39604727, 2025). "Genetic ablation of only Ptgs2 also led to re-sensitization of RTT tumours to ACT." (PMID 39604727, 2025). "All these data indicated MFAP2 may aggravate tumor progression through PTGS2 signaling which has been proven to be a tumor driver." (PMID 40657371, 2025). "The inability of tumor lines to produce PGE2 renders them highly susceptible to cDC1-dependent CD8+ T-cell-mediated immune control, and researchers have exploited preclinical Ptgs1/Ptgs2-/- tumor models to characterize the mechanisms controlling cDC1 accumulation." (PMID 40410571, 2025). "Furthermore, our analysis uncovered a high expression of PTGS2 (Prostaglandin-Endoperoxide Synthase 2), with a fivefold or greater increase observed in 68% of the tumor samples." (PMID 38979413, 2024). "PTGS2 is involved with angiogenesis in various tumor diseases." (PMID 36768450, 2023).